PLA2G6 (phospholipase A2 group VI)
Diseases named in the same sentence as PLA2G6 in open-access papers (continued):
Sharing a sentence is not in itself a finding about the gene and the disease.
Ataxia (11 papers, 2011 to 2025). Ataxia refers to impaired coordination of voluntary muscle movement. "In subsequent reports, additional phenotypes were identified, such as ataxia and complicated forms of spastic paraplegia, indicating the broad spectrum of presentations associated with PLA2G6 variants." (PMID 40263418, 2025). "INAD1/NBIA2A caused by mutations in PLA2G6 gene starts typically between ages 6 months and 3 years with rapid progression of truncal hypotonia, progressive psychomotor delay, cerebellar ataxia, symmetric pyramidal tract signs and tetraparesis (usually spastic but sometimes areflexic)." (PMID 24130795, 2013). "Cerebellar ataxia is an early symptom of INAD patients with PLA2G6 mutations." (PMID 22046428, 2011). "Eleven patients showed very early-onset ataxia and CA with cortical hyperintensities caused by mutations in ITPR1, KIF1A, SPTBN2, PLA2G6, PMPCA, and PRDX3." (PMID 36233161, 2022). "Later in the disease course, there are clinical differences with PLA2G6 cases having ataxia, greater Parkinsonian features and a better response to L-Dopa." (PMID 22416811, 2013).
Neurodegeneration (10 papers, 2014 to 2025). Progressive loss of neural cells and tissue. "Mutations in the PLA2G6 gene have variable phenotypic outcomes, so these different clinical groups have recently been collectively referred to as PLA2G6-associated neurodegeneration (PLAN)." (PMID 38384479, 2024). "PLA2G6-Associated with Neurodegeneration (PLAN) should be considered as a diagnosis in children with developmental regression." (PMID 36694760, 2023). "PLA2G6-associated neurodegeneration (PLAN) is the second core NBIA syndrome (NBIA type II, OMIM 256600 and 610217) and is associated to mutations in the PLA2G6 gene." (PMID 24847269, 2014).
Obesity (9 papers, 2011 to 2026). Accumulation of substantial excess body fat. "Further extended GWAS also identified a strong association of PLA2G6 to BFP in metabolically healthy obesity." (PMID 32957701, 2020). "Thus, PLA2G6 or iPLA2β may exhibit a unique activity with a preference toward obesity and hence obese NAFLD." (PMID 32957701, 2020). "Hence, iPLA2β or PLA2G6 may represent a key PL-metabolizing enzyme being critical in the development of obesity and Type-2 diabetes." (PMID 32957701, 2020). "For example, of the four loci discovered by the recently discussed GWAS in BF% (in or near COBLL1/GRB14, IGF2BP1, PLA2G6, CRTC1) and in the most recent GWAS of obesity as measured by BMI only a very small number of these overall obesity loci exhibited sexual dimorphism (approximately 3–5%)." (PMID 28073971, 2017). "Consistent with our hypothesis, HFr promoted significant AS changes in LWT mice and LΔRbfox2 mice failed to induce obesity-specific AS events at Pla2g6, Scarb1 and Numb." (PMID 36536133, 2022). "Whereas PLA2G6 is known to be a proinflammatory mediator required for monocyte chemotaxis and potentially contributory to both atherosclerosis and diabetes, the link between both PLAG4B & PLB1 and obesity, diabetes, or cardiovascular diseases is currently unknown." (PMID 41186047, 2026). "Interestingly unlike PLA2G6, group IVA PLA2 or group VIB iPLA2 (iPLA2γ) are not included in human GWAS data on obesity/adiposity and blood lipids." (PMID 32957701, 2020).
schizophrenia (9 papers, 2008 to 2025). A major psychotic disorder characterized by abnormalities in the perception or expression of reality. "One potential contributor to the niacin-induced flush abnormality in schizophrenia examined in this study is the genetic variants of PLA2G6 (rs4375)." (PMID 35853900, 2022). "When the distributions of the genetic variants of PLA2G6 (encoding calcium-independent PLA2 beta) were compared between schizophrenia patients and controls, one study in Brazilians29 found a significant difference but three studies in Chinese30 or Croatians31,32 did not." (PMID 35853900, 2022). "This study indicated that in the discovery stage, an increased copy number of PLA2G6 and the deletion of PLA2G3, PLA2G4A, PLA2G4F and PLA2G12F was associated with increased risk of schizophrenia." (PMID 38816399, 2024). "Both the schizophrenia patients (n = 46) and healthy controls (n = 37) were similar in the distribution of sex, age, length of follow-up, and the genotypes of PLA2G6 rs4375, but the patients had a higher prevalence of tobacco smoking than the controls." (PMID 35853900, 2022). "It is perhaps not inconceivable that in schizophrenia patients with such heterozygous PLA2G6 variants, antipsychotic treatment can trigger parkinsonian symptoms." (PMID 38028602, 2023). "We then examined whether the composite niacin flush score at baseline was associated with PLA2G6 genotype (rs4375), which was grouped into the presence of C (i.e., CC or CT) and absence of C (i.e., TT), separately for schizophrenia patients and healthy controls." (PMID 35853900, 2022).
pantothenate kinase-associated neurodegeneration (8 papers, 2013 to 2022). "The four most common NBIA forms are pantothenate kinase-associated neurodegeneration (PKAN), phospholipase A2 group VI (PLA2G6)-associated neurodegeneration (PLAN), beta-propeller protein-associated neurodegeneration (BPAN) and mitochondrial membrane protein-associated neurodegeneration (MPAN)." (PMID 33935938, 2021). "The four most common forms are pantothenate kinase-associated neurodegeneration (PKAN), phospholipase A2 group VI (PLA2G6)-associated neurodegeneration (PLAN), beta-propeller protein-associated neurodegeneration (BPAN) and mitochondrial membrane protein-associated neurodegeneration (MPAN)." (PMID 33935938, 2021). "Among them, the core syndromes are pantothenate kinase-associated neurodegeneration (PKAN, NBIA type 1), which was previously named Hallervorden-Spatz disease and accounts for approximately 50% of NBIA cases, and PLA2G6-associated neurodegeneration (PLAN, NBIA type 2)." (PMID 24348190, 2013). "In addition to the core syndromes of pantothenate kinase-associated neurodegeneration (PKAN, NBIA1) and PLA2G6-associated neurodegeneration (PLAN, NBIA2), several other genetic causes have been identified (including FA2H, C19orf12, ATP13A2, CP and FTL)." (PMID 23814539, 2013).
Cerebellar atrophy (7 papers, 2011 to 2024). Cerebellar atrophy is defined as a cerebellum with initially normal structures, in a posterior fossa with normal size, which displays enlarged fissures (interfolial spaces) in comparison to the foliae secondary to loss of tissue. "In this study, we used a mouse model of INAD to investigate potential mechanisms of cerebellar atrophy — a hallmark of INAD patients with PLA2G6 mutations." (PMID 22046428, 2011). "Marked cerebellar atrophy is the most characteristic MRI feature of INAD patients and observed in almost all INAD patients with mutations in PLA2G6, suggesting a neuropathologic role of dysfunctional iPLA2β in the cerebellar atrophy in the INAD patients." (PMID 22046428, 2011). "It’s noteworthy that genetic knockdown of PLA2G6 in mice (iPLA2b-/-) was documented to lead to the development of cerebellar atrophy by the age of 13 months." (PMID 24130795, 2013). "Here we show that genetic ablation of PLA2G6 in mice (iPLA2β-/-) leads to the development of cerebellar atrophy by the age of 13 months." (PMID 22046428, 2011). "Molecular testing for PLA2G6 mutations is, therefore, indicated in childhood-onset ataxia syndromes, if neuroimaging shows cerebellar atrophy with or without evidence of brain iron accumulation." (PMID 24130795, 2013). "Molecular testing for PLA2G6 mutations is, therefore, indicated in childhood-onset ataxia syndromes, if neuroimaging shows cerebellar atrophy with or without evidence of iron accumulation." (PMID 24130795, 2013). "MRI assessment showed absence of bilateral "swallow tail sign" and cerebellar atrophy in this patient, while no obvious difference in brain iron accumulation between PLA2G6 mutant PD patient and healthy controls." (PMID 31496990, 2019).
diabetes (6 papers, 2011 to 2026). "These included proteins expressed by pancreatic islet cells (Ptch1, Disp1, Pck1, and Cacna1e) as well as proteins known to be associated with diabetes mellitus susceptibility or glucose metabolism (Adcy8, Perm1, Sorbs1, and Pla2g6)." (PMID 37934865, 2023). "Mice used in these studies included spontaneous diabetes–resistant C57BL/6J, spontaneous diabetes–prone NOD, and NOD.PLA2G6+/–." (PMID 32814707, 2020).
neurodegeneration with brain iron accumulation (6 papers, 2010 to 2024). "In particular, mutations in PLA2G6 were identified in a locus for infantile neuroaxonal dystrophy (INAD) and neurodegeneration with brain iron accumulation (NBIA)." (PMID 34299248, 2021). "The 2 major types of neurodegeneration with brain iron accumulation (NBIA) are the pantothenate kinase type 2 (PANK2)-associated neurodegeneration (PKAN) and NBIA2 or infantile neuroaxonal dystrophy (INAD) due to mutations in the phospholipase A2, group VI (PLA2G6) gene." (PMID 20619503, 2012).
nevus (6 papers, 2017 to 2026). Nevus (or naevus, plural nevi or naevi, from nævus, Latin for "birthmark") is the medical term for sharply circumscribed[1] and chronic lesions of the skin or mucosa. "The analysis confirmed previously established nevus-associated loci (MTAP, PLA2G6, IRF4) and uncovered novel associations with single-nucleotide polymorphisms (SNPs) in KITLG and a region on chromosome 9q32." (PMID 41596618, 2026). "CMM tissue had a higher level and nevus tissue had a lower level of PLA2G6 expression." (PMID 35340268, 2022).
cognitive decline (5 papers, 2011 to 2022). "Adult-onset of PLA2G6-associated neurodegeneration is frequently accompanied by progressive and striking psychiatric deficits and cognitive decline." (PMID 29440694, 2018).
neuroblastoma (4 papers, 2015 to 2022). Neuroblastoma (NB) is the most common solid, extracranial childhood tumor. "Furthermore, the observation of strong α-syn expression in both PLA2G6 knockdown neuroblastoma cells and PLA2G6 mouse neurons indicated that PLA2G6 deficiency resulted in the induction of endogenous α-syn in neurons." (PMID 35795234, 2022). "To clarify the relationship between αSyn and PLA2G6 dysfunction in cultured neurons, we analyzed the expression level of αSyn in Pla2g6-Kd SH-SY5Y human neuroblastoma cells." (PMID 27030050, 2016). "The increased expressions of the molecules involved in iron homeostasis, particularly DMT1 and IRP2, were also demonstrated in the brains of aged iPLA2β-KO mice as well as in PLA2G6-KD SH-SY5Y human neuroblastoma cells." (PMID 26506412, 2015). "We have already established cultures of PLA2G6-KD SH-SY5Y human neuroblastoma cells." (PMID 26506412, 2015). "To clarify the mechanism underlying iron accumulation in the brains of iPLA2β-KO mice, we investigated the expression of molecules that are involved in iron homeostasis, including DMT1 and IRPs, in the brains of iPLA2β-KO mice as well as in PLA2G6 knockdown (KD) SH-SY5Y human neuroblastoma cells." (PMID 26506412, 2015).
dementia (3 papers, 2012 to 2023). Loss of intellectual abilities interfering with an individual's social and occupational functions. "Hippocampal involvement was also described by Michelis and colleagues, reporting a novel PLA2G6 mutation in a 35‐year‐old patient with adult‐onset autosomal recessive parkinsonism and early stages of dementia." (PMID 37139542, 2023).
hereditary spastic paraplegia (3 papers, 2021 to 2024). Hereditary spastic paraplegias (HSP) comprise a genetically and clinically heterogeneous group of neurodegenerative disorders characterized by progressive spasticity and hyperreflexia of the lower limbs. "Mutations in PLA2G6 have also been reported to be associated with a continuous clinical spectrum ranging from NAD to hereditary spastic paraplegia (HSP), a group of motor neurodegenerative disorders mainly characterized by slowly progressive spasticity and weakness of the lower limbs." (PMID 38384479, 2024).
Insulin resistance (3 papers, 2012 to 2026). Increased resistance towards insulin, that is, diminished effectiveness of insulin in reducing blood glucose levels. "However, PLA2G6 deficiency in both cell types exacerbated insulin resistance." (PMID 42101094, 2026). "We highlight two phospholipase encoding genes, PLA2G12A and PLA2G6, which liberate arachidonic acid and improve insulin sensitivity, and VGLL3, a transcriptional co-factor that increases insulin resistance partially through enhanced adiposity." (PMID 39277575, 2024).
lung carcinoma (3 papers, 2016 to 2022). "One candidate gene pathway analysis identified PLA2G6, a member of the cell cycle pathway, as bearing a statistically significant single nucleotide polymorphism associated with lung cancer risk." (PMID 27602958, 2016).
ovarian carcinoma (3 papers, 2018 to 2021). A malignant neoplasm originating from the surface ovarian epithelium. "Downregulation of PLA2G6 expression inhibited cell proliferation in culture, and tumorigenicity of ovarian cancer cell lines in nude mice." (PMID 29890619, 2018).
Stroke (3 papers, 2017 to 2025). Sudden impairment of blood flow to a part of the brain due to occlusion or rupture of an artery to the brain.
Type-2 diabetes (3 papers, 2020 to 2026). "In this study, the BFP-increasing allele in the locus near PLA2G6 is associated with lower plasma TG levels in men and women, with lower insulin levels and risk of Type-2 diabetes particularly in men, and higher visceral adipose tissue in men." (PMID 32957701, 2020). "Polymorphisms of group VIA calcium-independent phospholipase A2 (iPLA2β or PLA2G6) are positively associated with adiposity, blood lipids, and Type-2 diabetes." (PMID 32957701, 2020). "Furthermore, genetic variants at or near PLA2G6 are associated with Type-2 diabetes in European-Americans, European-American women, and a Chinese population." (PMID 32957701, 2020).
breast carcinoma (2 papers, 2023 to 2024). "PLA2G6 and SLC25A26 have been identified as involved in the development of various tumors, though their link to breast cancer is still underexplored." (PMID 39720180, 2024).
developmental delay (2 papers, 2013 to 2025). "In our cohort, several genes were frequently implicated in cases of genetic epilepsy and developmental delay, including PRRT2 (n:2), KCNQ2 (n:2), SCN1A (n:2), PLA2G6 (n:2), and KDM6A (n:2)." (PMID 40083435, 2025).
frontotemporal dementia (2 papers, 2013 to 2018). Frontotemporal dementia (FTD) comprises a group of neurodegenerative disorders, characterized by progressive changes in behavior, executive dysfunction and language impairment, as a result of degeneration of the medial prefrontal and frontoinsular cortices. "However, changes in several other genes have been suggested as causes for recessive neurological/neurodegenerative disorders that may include PD: hereditary ataxias (ATXN2/3, FMR1), frontotemporal dementia (e.g. MAPT) and others (e.g. ATP13A2, PLA2G6, FBXO7)." (PMID 23976986, 2013).
Hepatic steatosis (2 papers, 2025). Steatosis is a term used to denote lipid accumulation within hepatocytes. "Pla2g6 deficiency attenuates hepatic steatosis in obese mice and is identified as one of the MAFLD modifier genes." (PMID 40760121, 2025).
liver disease (2 papers, 2025 to 2026). "Silymarin/silybin regulates a significant number of these lipid metabolic genes, including iPLA2/PLA2G6, ATGL/PNPLA2, PLD1, LPIN2, and by trend PNPLA3 (which is a major genetic risk factor for MAFLD 131) and HSD17B13, counteracting the observed dysregulation in liver diseases." (PMID 39897559, 2025).
Niemann-Pick disease type C (2 papers, 2021 to 2022). NPC is a complex lipid storage disease mainly characterized by the accumulation of unesterified cholesterol in the late endosomal/lysosomal compartment. "Neurofibrillary tangles in young patients are seen only in rare conditions such as Niemann–Pick’s disease type C, subacute sclerosing panencephalitis, and genetic syndromes linked to PLA2G6 and SLC9A6 mutations." (PMID 35563179, 2022). "The differential diagnosis of known progressive ataxias with leukoencephalopathy included mitochondriopathies, ceroid lipofuscinosis, sialidosis, GM2 gangliosidosis, Niemann Pick type-C disease, and PLA2G6-associated neurodegeneration." (PMID 33804237, 2021).
sarcoidosis (2 papers, 2020 to 2023). Sarcoidosis is a multisystemic disorder of unknown cause characterized by the formation of immune granulomas in involved organs. "According to Gini score calculated from gene expression values, we examined the top-6 most important AA metabolism-related genes (including PLA2G6, PLA2G7, AKR1C1, AKR1C3, LTA4H, and PTGER4) in sarcoidosis, whose expression showed a positive correlation with sarcoidosis samples." (PMID 33097805, 2020).
Wilson disease (2 papers, 2021 to 2022). A very rare inherited multisystemic disease presenting non-specific neurological, hepatic, psychiatric or osseo-muscular manifestations due to excessive copper deposition in the body. "Autosomal recessive: This subgroup includes forms, such as DYT-ATP7B, also known as Wilson disease, NBIA/DYT-PANK2 or pantothenate kinase-associated neurodegeneration (PKAN), and NBIA/DYT/PARKa-PLA2G6 or PLA2G6-associated neurodegeneration (PLAN)." (PMID 33604773, 2021).
Alzheimer disease (1 paper, 2014). A progressive, neurodegenerative disease characterized by loss of function and death of nerve cells in several areas of the brain leading to loss of cognitive function such as memory and language. "Furthermore, the expression of DHA selective iPLA2 VIA (PLA2G6) is reduced in Alzheimer's disease, but we found that its expression is increased in Aging, which shows another disconnection between healthy and pathological aging." (PMID 24963629, 2014).
Atrophy (1 paper, 2011). Any weakening or degeneration, especially through lack of use. "Our findings indicate that the absence of PLA2G6 causes neuroinflammation and Purkinje cell loss and ultimately leads to cerebellar atrophy." (PMID 22046428, 2011).
benign melanocytic nevus (1 paper, 2022). "Based on the Oncomine database, we found that the mRNA level of PLA2G6 was up-regulated in CMM compared with the benign melanocytic nevus." (PMID 35340268, 2022).
cutaneous malignant melanoma (1 paper, 2022). "Although phospholipase A2 group VI (PLA2G6) is involved in oncogenesis in several human tumors, its expression and role in cutaneous malignant melanoma (CMM) pathogenesis remains unclear." (PMID 35340268, 2022).
dilatation (1 paper, 2023). "Those indicate LV systolic dysfunction without LV dilatation in the TAC-operated Pla2g6+/+ hearts." (PMID 37524709, 2023).
early-onset dystonia-parkinsonism (1 paper, 2020). "One of these is PARK14/PLA2G6, a disease locus for a collection of neurodegenerative disorders including early-onset dystonia-parkinsonism (collectively called PLA2G6 Associated Neurodegeneration, PLAN)." (PMID 32282825, 2020).
essential tremor (1 paper, 2022). A relatively common disorder characterized by a fairly specific pattern of tremors which are most prominent in the upper extremities and neck, inducing titubations of the head. "In the porphyrin metabolic pathway, higher serum bilirubin contents have been observed in patients with PD, essential tremor (ET), and PLA2G6 mutations (our study)." (PMID 36033628, 2022).
Hepatic fibrosis (1 paper, 2019). The presence of excessive fibrous connective tissue in the liver. "Our results may have implications on individuals with hepatic fibrosis and cholangiopathies with PLA2G6 mutations who exhibit NASH or consume choline-deficient diet." (PMID 31409057, 2019).